NOTCH3 (notch receptor 3)
Diseases named in the same sentence as NOTCH3 in open-access papers (continued):
Sharing a sentence is not in itself a finding about the gene and the disease.
bladder cancer (11 papers, 2017 to 2025). "Furthermore, Notch 3 was shown to be overexpressed in bladder cancer and is associated with poorer treatment outcomes." (PMID 34059639, 2021). "In contrast, c-MET resulted as a co-lesion with NOTCH 3 and FBXW7 in one of the patients of our analysis, thus suggesting the potential use of Crizotinib, a multi-target tyrosine kinase inhibitor (TKI) in bladder cancer in this mutational setting." (PMID 41008920, 2025). "This supports the oncogenic role of the NOTCH2/NOTCH3/DLL4 axis in bladder cancer." (PMID 41008920, 2025). "Indeed, silencing of NOTCH3 in two bladder cancer cell lines sensitised one cell line to cisplatin, which is known to inhibit the SERCA pump, just like the recently discovered CAD204520 that can block oncogenic NOTCH." (PMID 41008920, 2025). "Although alterations in SPP1 gene have been reported but poorly represented in bladder cancer (2.19% of 411 bladder cases, we can hypothesise that NOTCH3-triggered molecular mechanism may be the prevailing one." (PMID 41008920, 2025). "Although influential studies by Rampias and Maraver reported NOTCH1 and NOTCH2 mutations in bladder cancer, NOTCH3 was not studied." (PMID 41008920, 2025). "Based on a large cohort of patients, derived from the integration of four independent genome-wide studies in bladder cancer, our analysis distinguishes NOTCH3 mutations in non-muscle-invasive bladder cancer from muscle-invasive cases." (PMID 41008920, 2025). "The biological role and precise molecular mechanisms of Notch receptor 3 (NOTCH3) in the malignant progression of bladder cancer (BLCA) remain unclear." (PMID 39557868, 2024). "For example, CHIR upregulates both β-catenin and Notch3 proteins in non-small lung cancer cell lines, although functional relevance of Notch3 in bladder cancer is unknown compared to Notch1 and Notch2." (PMID 29541396, 2018). "Thus, considering the high-rate mutation of NOTCH3 in BCa, this SERCA inhibitor could be considered in preclinical bladder cancer therapy studies." (PMID 41008920, 2025). "Treatment of T24 bladder cancer cells with vorinostat upregulated Notch3 protein-acetylation levels, decreased Notch3 expression, reduced proliferation and induced cell-cycle arrest, thus indicating the integration of vorinostat in bladder cancer therapeutic schemes." (PMID 30875794, 2019). "Moreover, different Notch paralogs may have different actions in cancerous transformation; for example, it has been described that NOTCH1 and NOTCH3 have disparate roles from NOTCH2 in bladder cancer." (PMID 28915655, 2017).
lateral meningocele syndrome (11 papers, 2020 to 2025). "Truncation of NOTCH3 in the Lateral Meningocele Syndrome, is associated with cardiac defects, including aortic anomalies and septal defects." (PMID 40163542, 2025). "Our analysis in the mouse is supported by observations in a patient cohort, identifying novel rare NOTCH3 variants associated with cardiac defects similar to that found in Lateral Meningocele Syndrome or in heterotaxy." (PMID 40163542, 2025). "Down-regulation of Notch3 expression via systemic administration of Notch3-specific ASOs in a Notch3 gain-of function mutation (Notch3em1Ecan) mouse model of lateral meningocele syndrome ameliorates cortical osteopenia associated with the mice (Ref." (PMID 36052538, 2022). "Recently, we created a mouse model harboring a Notch3 mutation designed to reproduce the functional outcome of lateral meningocele syndrome and termed Notch3em1Ecan (synonym Notch3tm1.1Ecan)." (PMID 33774049, 2021). "It is possible that the pathogenic variant associated with Lehman Syndrome can be targeted to ameliorate the phenotype associated with the NOTCH3 gain-of-function using an ASO approach." (PMID 33519922, 2020). "Lateral meningocele syndrome (LMS) is due to specific pathogenic variants in the last exon of NOTCH3 gene." (PMID 32141180, 2020). "In comparison, truncating NOTCH3 mutations within exon 33 (often deletions of stop-loss mutations) which disrupts the NOTCH3 PEST domain are also known to cause lateral meningocele syndrome (LMS) MIM#130720." (PMID 31915071, 2020). "The present studies were conducted to determine whether a NOTCH3 pathogenic variant found in LMS or Lehman Syndrome had a phenotypic impact on mesenchymal and osteogenic cell differentiation." (PMID 39752389, 2025). "Lehman Syndrome or Lateral meningocele syndrome (LMS) (Online Mendelian Inheritance in Man 130720) is a devastating monogenetic disorder associated with pathogenic variants of NOTCH3." (PMID 35536858, 2022). "Lateral Meningocele Syndrome (LMS), a disorder associated with NOTCH3 pathogenic variants, presents with neurological, craniofacial and skeletal abnormalities." (PMID 39752389, 2025). "These defects are similar to those found in Notch3−/− mouse mutants and in patients with Lateral Meningocele syndrome." (PMID 40163542, 2025). "The present work demonstrates that Notch3 ASOs downregulate Notch3 mRNA in cells from wild type and Notch3em1Ecan mice, a preclinical model of Lehman Syndrome (LMS)." (PMID 35536858, 2022). "Previously, we reported a mouse model (Notch3em1Ecan or Notch3tm1.1Ecan) of lateral meningocele syndrome presenting with NOTCH3 gain of function due to stabilization of NOTCH3 and osteopenia." (PMID 33774049, 2021). "We now observe cardiac defects typical of Lateral Meningocele syndrome in homozygote Notch3 mouse mutants and in other patients with NOTCH3 variants not in exon 33, but in the EGF-like repeats." (PMID 40163542, 2025). "Lateral Meningocele Syndrome (LMS) is a monogenic disorder associated with NOTCH3 pathogenic variants that result in the stabilization of NOTCH3 and a gain-of-function." (PMID 35536858, 2022).
lymph node metastasis (11 papers, 2012 to 2025). "NOTCH3+ CAFs are associated with advanced disease, larger tumors, lymph node metastasis, and poorer prognosis." (PMID 39928309, 2025). "Ye and her co-workers discovered that Notch3 was associated with lymph node metastasis and poor prognosis." (PMID 35118116, 2021). "Nuclear Notch3 was associated with the presence of lymph node metastases in resected PDAC specimens (p = 0.015) and there was a trend towards association with tumour stage (p = 0.07), but not with other clinicopathological features." (PMID 23226563, 2012). "We found that Notch3 expression and pS6 expression were negatively associated with age (p > 0.05) but were positively associated with clinical stage, pathological grading, histological type, lymph node metastasis, and ascites." (PMID 27445438, 2016). "In tumor tissues, Notch3 expression and pS6 expression were negatively associated with age (p > 0.05) but positively associated with clinical stage, pathological grading, histologic type, lymph node metastasis, and ascites (p < 0.05 or p < 0.01)." (PMID 27445438, 2016). "However, Notch 3 was only associated with lymph node metastasis." (PMID 25996086, 2015). "High Notch3 mRNA expression correlated significantly with worse overall survival and clinical chemoresistance, and Notch3 protein overexpression was significantly associated with the prognostic parameters advanced stage disease, lymph node metastases and distant metastases." (PMID 25366565, 2014). "All data indicate that Notch3 expression positively correlates with elevated expression of GATA-3, ER and PR, as well as with a lower risk of lymph node metastasis." (PMID 30100605, 2018). "In addition, overexpression of Notch3 has been significantly correlated with advanced stage, lymph node metastasis, chemoresistance and poor overall survival." (PMID 29104587, 2017). "Importantly, expression of Notch3 has been related to lymph node metastasis." (PMID 29104587, 2017). "OSCCs with NOTCH3-positive CAFs are associated with significantly larger tumor size (P = 0.0292) and lymph node metastasis (P = 0.0023) compared to OSCCs without NOTCH3-positive CAFs." (PMID 27124156, 2016). "The expression of Notch3 and pS6 was higher in serous cystadenocarcinoma, lymph node metastasis, and ascites than in mucinous cystadenocarcinoma (p < 0.01, p < 0.05) and in the absence of lymph node metastasis (p < 0.01, p < 0.01) and ascites (p < 0.01, p < 0.01)." (PMID 27445438, 2016). "Moreover, we found that Notch3 and/or GATA-3 negative patients exhibited more lymph node metastases; this implies that the absence or low expression of Notch3/GATA-3 may indicate a high potential for metastasis." (PMID 30100605, 2018).
T-cell acute lymphoblastic leukemia (11 papers, 2017 to 2025). Acute lymphoblastic leukemia of T-cell origin. "Only a few genes, such as HES4, HEY1, MYC, NOTCH3, NRARP, and TFRC, are similarly regulated in mutationally activated NOTCH1-driven cancers, such as T-cell acute lymphoblastic leukemia (T-ALL), mantle cell lymphoma (MCL), and breast cancer." (PMID 33003595, 2020). "We recently reported that in a transgenic murine model of Notch3-dependent T-cell acute lymphoblastic leukemia there is an accumulation of myeloid-derived suppressor cells, dependent on both Notch signaling deregulation and IL-6 production inside tumor T-cells." (PMID 39337370, 2024). "Notch3 acetylation/deacetylation represents a key regulatory switch in the control of Notch signaling, and represents a suitable drug target for Notch3-sustained T-cell acute lymphoblastic leukemia therapy." (PMID 28416766, 2017). "We previously demonstrated the oncogenic potential of Notch3 in transgenic (tg) mice, overexpressing the constitutively active intracellular domain of Notch3 (N3-IC) in immature thymocytes, which develop an aggressive T-cell ALL, recapitulating most of human T-ALL features." (PMID 30038265, 2018). "In T-cell acute lymphoblastic leukemia, the intracellular domains of NOTCH1 and NOTCH3 are effectively interchangeable in their ability to drive the expression of downstream target genes that support the aberrant cell growth." (PMID 32908186, 2020). "In other cellular contexts, it has also been observed that NOTCH1 and NOTCH3 signaling is very similar, for example in acute T-cell lymphoblastic leukemia, in which the activation of both NOTCH1 and NOTCH3 has the ability to induce T-ALL64." (PMID 32908186, 2020).
endometrial cancer (10 papers, 2018 to 2025). Primary or metastatic malignant neoplasm involving the endometrium (mucous membrane that lines the endometrial cavity). "Circ_0000043 (circ_PUM1) is an example of circRNAs contributing to the progression of endometrial cancer through regulation of NOTCH 3 expression." (PMID 40761890, 2025). "For example, in endometrial cancer, circ_PUM1 can increase Notch3 by sponging miR-13, thus, promoting the development of endometrial cancer." (PMID 34912799, 2021). "In conclusion, our data suggest that circ_PUM1 plays a critical role in the development and progression of endometrial cancer, mainly by adsorbing miR‐136 via a ‘sponge’ effect and thereby promoting expression of the target gene NOTCH3." (PMID 32073729, 2020). "Circ_PUM1 can compete with miR‐136, leading to up‐regulation of NOTCH3, and thereby promote the development of endometrial cancer." (PMID 32073729, 2020). "Together, these data suggest that circ_PUM1 promotes the development of endometrial carcinoma by targeting protein NOTCH3 via miR‐136." (PMID 32073729, 2020). "The fact that Notch signaling protein expression is increased in human endometrial carcinoma cells compared with that in healthy endometrial cells is in line with the assumed effect of NOTCH3 in proliferation and differentiation." (PMID 33029756, 2020). "It was found that circ_PUM1 could compete with miRNA-136, resulting in upregulation of NOTCH3 expression, thus, promoting the occurrence and development of endometrial carcinoma." (PMID 34178035, 2021). "Beyond classic unfavorable prognostic factors in endometrial cancer, such as tumor type II, higher grade and more advanced stage, higher Ki67 labeling, expression of the PTEN, p16, Notch2 and Notch3 proteins, as well as MMR proficiency were associated with increased relapse and mortality risk." (PMID 30521558, 2018). "Also, as compared to low endometrial cancer grades, tumours with grade 3 were more frequently characterized with NOTCH2 and NOTCH3 protein overexpression." (PMID 35136410, 2022).
T-cell leukemia (10 papers, 2013 to 2022). A malignant disease of the T-lymphocytes in the bone marrow, thymus, and/or blood. "Moreover, enforced expression of the active intracellular domain of Notch3 (Notch3-ICD) has been reported to cause T-cell leukemia in mouse models." (PMID 29643474, 2018). "Overall, our study supports previous researches indicating GSKJ4 as a promising therapeutic agent in Notch1- and TAL1- dependent T-ALL, while laying the basis for extending its potential use also to Notch3- and c-Myc- dependent T-cell leukemia contexts." (PMID 31001470, 2019). "We have previously shown that Notch3 receptor constitutively localizes to lipid rafts of Notch3 overexpressing lymphocytes, thus contributing to sustain the signaling pathways responsible of the T-cell leukemia development." (PMID 29795369, 2018). "Overall, our findings provide new insights unveiling a possible dual mechanism focused on phosphorylation-dependent prolyl-isomerization by Pin1 as responsible for sustained Notch3-IC expression and signaling in T-cell leukemia." (PMID 26876201, 2016). "In the Notch3 transgenic mouse model, HDAC inhibitor-mediated hyperacetylation of Notch3 inhibits the proliferation of T cell leukemia/lymphoma cells." (PMID 26075180, 2015). "In tumorigenesis, NOTCH3 has been shown to induce T cell leukemia through the activation of NF-kB." (PMID 36382054, 2022). "Notably, the increased number of N3high and the ratio N3high/N3low DP cells infiltrating the spleen further highlight the environmental requirements to sustain Notch3+highCXCR4+highDP “fitness” in T-cell leukemia propagation." (PMID 30038265, 2018). "Altogether, targeting Notch3 deacetylation could be a promising therapeutic strategy for T-cell leukemia." (PMID 26075180, 2015). "The non-acetylatable Notch3 mutant can enhance Notch3-induced growth of T cell leukemia proliferation, which can be blocked by a histone deacetylases (HDAC) inhibitor." (PMID 26075180, 2015). "Hes5, Notch3 and Hes4 genes were either not expressed or very weakly expressed in highly methylated B leukemia cell lines but were abundantly expressed in unmethylated T cell leukemia cell lines such as T-ALL1 and SupT1." (PMID 23637910, 2013).
diabetes (9 papers, 2012 to 2025). "Although ischemia and traumatic brain injury are extreme examples, many factors can contribute to more subtle BBB damage, such as metabolic diseases (diabetes and obesity), genetics (NOTCH3), and vascular risk factors." (PMID 27654972, 2016). "Venn diagram analysis revealed that seven DEGs (CXCL8, MLXIPL, CREB3L1, EGR1, NOTCH3, ACTA2, and SERPINE1) were associated with both obesity and diabetes-associated pathways, including non-alcoholic fatty liver disease, insulin resistance, thermogenesis, and apelin signaling pathways." (PMID 38570815, 2024). "We speculate that NOTCH3 gene mutations may interfere with the Dll4-NOTCH3 pathway thereby causing blood glucose abnormalities, which suggests that we investigate the association between the CADASIL clinical phenotype and diabetes through more clinical series." (PMID 41018180, 2025). "A whole-transcriptome study revealed differentially expressed target genes important in obesity and diabetes-related pathways such as MLXIPL, CREB3L1, EGR1, ACTA2, SERPINE1, NOTCH3, and CXCL8." (PMID 38570815, 2024).
liver cancer (9 papers, 2015 to 2025). An epithelial or non-epithelial malignant neoplasm that arises from the liver. "In liver cancer, CAFs induce the expression of Notch3, promoting the proliferation of tumor stem cells." (PMID 41050674, 2025). "Recent studies have shown that the NOTCH3 signaling pathway is closely related to the occurrence and development of liver cancer." (PMID 32311840, 2020). "Additionally, the Notch3 expression induced by liver cancer CAFs helps promote the proliferation of tumor stem cells." (PMID 41050674, 2025). "Furthermore, a high level of Notch3 expression indicated an unfavorable prognosis in liver cancer patients." (PMID 38169546, 2024). "Inhibiting Notch3 promotes GSK313 phosphorylation and downregulates p21, increasing the toxic effects of sorafenib on liver cancer cells." (PMID 28416766, 2017). "However, NOTCH3 expression has no prognostic value for patients with liver cancer." (PMID 33479597, 2020).
lymphoma (9 papers, 2009 to 2024). A malignant (clonal) proliferation of B- lymphocytes or T- lymphocytes which involves the lymph nodes, bone marrow and/or extranodal sites. "We also consulted multiple atlas to gather information regarding Notch 3 expression profiles in lymphomas." (PMID 33374160, 2020). "Real-time RT-PCR confirmed that Notch1, Notch3, Hes1 and Myc mRNA levels were upregulated in Lck-Dlx5 lymphomas, when compared with those of WT thymic T-cells and Lck-MyrAkt2 lymphomas." (PMID 28122332, 2017). "Immunohistochemistry also confirmed that Notch1, Notch3, Hes1, Myc and phospho (active)-Akt are upregulated in primary and metastatic lymphomas from Lck-Dlx5 mice." (PMID 28122332, 2017). "Overall, these data indicate that Pin1 deletion affects the Notch3-dependent tumor progression and invasion properties of lymphoma cells in vivo." (PMID 26876201, 2016). "Notch 3 sustains survival, proliferation and the invasion of lymphoma cells via different pathways." (PMID 33374160, 2020). "However, Hes1 transgenic mice develop lymphomas with a much longer latency and with a lower frequency compared to Notch1 or Notch3 expressing animals." (PMID 19688092, 2009). "Immunoblotting uncovered upregulation of Notch1/Notch3 in tumors from Lck-Dlx5 and Lck-Dlx5;Lck-MyrAkt2 mice, upregulation of Myc in tumors from Lck-Dlx5, Lck-MyrAkt2, and Lck-Dlx5;Lck-MyrAkt2 mice, and upregulation of β-catenin uniquely in lymphomas from Lck-Dlx5;Lck-MyrAkt2 mice." (PMID 32985581, 2020). "The majority of lymphomas also expressed high levels of CD25, consistent with previous studies of Notch3-induced T cell lymphomas." (PMID 19688092, 2009). "The reason why mRNA levels of Notch1 and Notch3 were 2–4 fold greater in lymphoma cells than in normal T cells from Lck-Dlx5 mice was not due to gene amplification, as array-CGH analysis revealed no change of Notch1/3 gene copy number." (PMID 28122332, 2017).
nasopharyngeal carcinoma (9 papers, 2015 to 2024). A carcinoma arising from the nasopharyngeal epithelium. "Moreover, inhibition of Notch3 signaling pathway significantly enhanced sensitivity to cisplatin in EBV-associated nasopharyngeal carcinoma." (PMID 28977931, 2017). "Additionally, the up-regulation of NOTCH3 was reported in SCC, and it has been associated with resistance to the 5-FU drug and reduced sensitivity to cisplatin in nasopharyngeal carcinoma." (PMID 39273632, 2024). "Similarly, Zhang and Li provided evidence that LINC00210-mediated silencing of the miR-328-3p/NOTCH3 pathway facilitated nasopharyngeal carcinoma development and progression." (PMID 34518442, 2021).